HK2 (hexokinase 2)
Diseases named in the same sentence as HK2 in open-access papers (continued):
Sharing a sentence is not in itself a finding about the gene and the disease.
tumor (continued). "Brassinin also exhibited anti-Warburg effects by suppressing glycolysis-related proteins like pyruvate kinase isoenzyme M2 (PKM2), glucose transporter 1 (Glut1), hexokinase 2 (HK2), and lactate dehydrogenase (LDH) in PC-3 cells, indicating an impact on the tumor’s energy metabolism." (PMID 38792249, 2024). "In addition, the results of IHC analysis showed that the expressions of CD8, GLUT1, HK2, PKM2 and LDHA were significantly up-regulated in tumor tissues treated with anti-TIGIT mAb." (PMID 38216949, 2024). "Our data indicate that detaching HK2 from MAMs could pave the way for a novel anti-MPNST therapeutic strategy, which could be flexibly adapted to the protease expression features of the tumor microenvironment." (PMID 38995012, 2024). "Studies have shown that the regulation of glycolysis involves glucose transporter type 1 (GLUT1), hexokinase 2 (HK2), the mitochondrial translocator protein (TSPO), lactate dehydrogenase A (LDHA), hypoxia‐inducible factor 1‐alpha (HIF‐1⍺), the tumor microenvironment, and mitochondrial genes." (PMID 39639571, 2024). "Moreover, the animal experiments further confirmed that KIAA1429 silencing diminished levels of YTHDF1, FOXM1, HK2, ENO1, and LDHA and suppressed tumor growth." (PMID 39060874, 2024). "Besides, HK2, LDHA and Ki67 positive cells also were decreased in the tumor tissues of sh-circ_0000376 group." (PMID 38218855, 2024). "As HK2 expression is closely related to the rate of fluoro-2-D-deoxyglucose F18 (18F-FDG) uptake in GC, we further analyzed the rates of 18F-FDG PET/CT of 30 GC patients with tumor relapse." (PMID 36114400, 2023). "Furthermore, due to the high proportion of hexokinase 2 (HK2)-positive PCs in tumors, reducing HK2/ROCK2 through shRNA or inhibitors can reduce the contractility of tumor PCs to rebuild the vascular system and thus improve drug delivery." (PMID 37666813, 2023). "Additionally, the tumor growth of OSCC cells was delayed in vivo and the glycolysis was notably decreased following HK2 knockdown." (PMID 37779163, 2023). "After xenotransplantation of HT29 and HCT116 cells into female athymic nude mice, the tumor weight of 10 mg/kg every 2 days in xanthohumol-treated mice was significantly reduced, and expression of Ki-67, p-AKT, and HK2 was downregulated, which was consistent with the results of in vitro experiment." (PMID 37693915, 2023). "Both HK2 and GAPDH are upregulated in many human tumours and serve as drug targets." (PMID 37390227, 2023). "Real-time qPCR analysis of glucose transporter and glycolytic genes in the xenograft tumor tissues showed that ACE2 overexpression suppressed the mRNA levels of SLC2A1, HK2, ENO1, PFKL, LDHA, and PDK1, while inhibition of Mas receptor with A779 restored the expression of glycolytic components." (PMID 37215979, 2023). "METTL3 increased HK2 and SLC2A1(GLUT1) mRNA stability and transcription levels through an m6A-IGF2BP2/3-dependent mechanism, then activated CRC glucose metabolism to facilitate cell proliferation and tumor growth in vitro and in vivo." (PMID 37152066, 2023). "HK2, PDK1, and LDHA are also reported to be key participants in the tumor glycolysis process." (PMID 37233956, 2023). "Interestingly, the mitochondrial TIGAR–HK2 complex upregulated HK2 and hypoxia-inducible factor 1 (HIF1) activity, which limits reactive oxygen species (ROS) production and protects against tumor cell death under hypoxic conditions." (PMID 37109475, 2023). "We found a positive correlation of HK2 expression levels with larger tumor sizes, progesterone receptor (PR)-negative expression, and higher Ki67 levels." (PMID 37377974, 2023). "Importantly, TEPP-46 treatment attenuated the expression of HIF-1α, HK2, and PKM2, an diminished glycolysis, STING phosphorylation, and type I IFN induction in tumor-infiltrating WT DCs." (PMID 36821379, 2023).
tumor (continued). "In our study, HK2, the predominant HK form in a wide range of malignancies, was generally not expressed by healthy urothelial cells, CAF, or tumour blood vessels, but 35.5% of the cancer cells expressed HK2." (PMID 36765947, 2023). "The results showed that compared to the sh-NC group, the lactate and ATP contents in tumor tissues were significantly reduced in the sh-LHX9 group, and the mRNA and protein expression of glycolysis-related genes (GLUT1, HK2, LDHA, and PDK1) were also significantly reduced." (PMID 37980488, 2023). "According to reports in the literature, the hypoxic environment stimulates the production of lactic acid in tumor cells by activating hypoxia-inducible transcription factor 1α (HIF-1α)-dependent genes such as glucose transporter 1 (GLUT1) and hexokinase 2 (HK2)." (PMID 35915188, 2022). "Moreover, Wong and co-workers elucidated that increased hexokinase 2 (HK2)-mediated pericyte glycolysis was capable of strengthening ROCK2-MLC2 axis-mediated contractility, thereby resulting in disrupted tumor vascular function." (PMID 36439137, 2022). "As an important regulator of Wnt transduction in the canonical signaling pathway in tumours, Dickkopf-related protein 3 (DKK3) negatively regulates aerobic glycolysis [HK2, HIF-1α, GLUT-1, LDHA and 3-phosphoinositide-dependent protein kinase-1 (PDK-1)] in BxPC-3 cells." (PMID 36578477, 2022). "Discovered overexpression of HK2, AK2, and AK6 isoforms in mitochondrial and nuclear compartments suggests that aggressive cancer cells use a strategy of microcompartmentation to support specific cellular functions and promote tumor growth." (PMID 35712500, 2022). "In an in vivo experiment, 10 mg/kg/d Lic A inhibited the growth of the cancer cell MKN45 xenograft model tumor, the expression of HK2 in tumor tissues was reduced significantly, but did not affect that weight of the mice." (PMID 36438836, 2022). "We selected hexokinase 2 (HK2), Hypoxia-inducible factor 1-alpha (HIF1A), glycolytic enzymes glucose transporter 1 (GLUT1) as well as GLUT3 that have been fully confirmed to participate in aerobic glycolysis in tumor for further validation." (PMID 34996491, 2022). "Therefore, HER4 promotes glycolysis and tumor growth in OS by upregulating c-myc positive regulation of glycolysis-related genes (GLUT1, HK2, KFPFB3, and PKM2)." (PMID 36059961, 2022). "Several HK2 inhibitors have been evaluated in vitro and in mouse models, but no successful agents that clinically suppress tumor HK2 have been discovered due to their low specificity to tumor cells." (PMID 36320008, 2022). "Additionally, critical glycolytic enzymes such as hexokinase 2 (HK2), phosphofructokinase, and enolase 1 (ENO1) were upregulated in the tumor model." (PMID 36358644, 2022). "In addition, downregulation of FBP2 notably reduced FBP2 protein expression and upregulated Ki67, GLUT1, HK2, PKM2, and LDHA protein expressions in tumor tissues." (PMID 35571245, 2022). "Besides, the expression of glycolytic enzymes, including GLUT1, HK2, and lactate dehydrogenase A (LDHA) was more in tumor cells after co-culture with TAMs." (PMID 35986343, 2022). "Our work demonstrates that targeting metabolic enzymes (SDHA, cPLA2, HK2) with specific inhibitors (EPIC, AA and 2-DG) could extremely decrease the ATP production rate in GBM cells, leading to tumor cell proliferation inhibition." (PMID 36276638, 2022). "The tumor hypoxic microenvironment can induce increased expression of c-Myc in tumor cells, facilitating aerobic glycolysis by enhancing c-Myc-mediated transcriptional regulation of key glycolysis genes, such as PKM2, GLUT1 and HK2 genes." (PMID 35927226, 2022). "In addition, HK2 has been adopted as an essential metabolic marker for the prognostic spectrum of NSCLC, as detected in circulating tumor cells (CTCs) in NSCLC patients." (PMID 36532721, 2022).
tumor (continued). "The upregulated SLC2A1 (GLUT1) (T/TA = 9.49), HK2 (T/TA = 36.69), PFKP (T/TA = 15.97), PKM (T/TA = 4.08), and LDHA (T/TA = 8.58) suggested the increased of glucose utilization for lactate fermentation in ccRCC tumor vs. adjacent tissues." (PMID 35440542, 2022). "Previous studies have confirmed that phosphofructokinase (PFK), hexokinase 2 (HK2), lactate dehydrogenase A (LDHA), and pyruvate kinase 2 (PKM2) are the key proteins in the metabolic pathway of tumor aerobic glycolysis, which are potential targets for tumor drug therapy." (PMID 36467556, 2022). "Licochalcone A suppressed hexokinase 2 (HK2) induced glycolysis in the human gastric BGC-823 cells, which not only inhibited proliferation and clonogenic survival but also induced apoptosis in the tumor cells." (PMID 35082907, 2022). "As expected, we discovered that like pan-cancer results, the expression of HK2 was significantly higher in tumor tissues in contrast to normal tissue samples (P value < 0.0001)." (PMID 35265223, 2022). "Pearson correlation analysis revealed that there is a significant negative correlation between MARCH8 and HK2 in CRC tumour tissues (R = -− 5672, P < 0.05)." (PMID 36064706, 2022). "TNF-α and IL-17 synergistically enhance glycolysis and lactate production in CRC HT-29 cells via activation of the NF-κB axis in tumor cells, and they promote GLUT1 and hexokinase 2 (HK2), as well as expression of the common target genes HIF-1α and c-myc which, in turn, promote tumorigenesis." (PMID 36588722, 2022). "Furthermore, we found that decreasing circ-RNF121 expression led to significant expression inhibition of HK2 and PKM2 in the forming tumor tissues, two key glycolytic enzymes." (PMID 34742305, 2021). "Of significance, deleting HK2 inhibits tumor progression with no sign of adverse physiological effects." (PMID 33753739, 2021). "To confirm that GCMSCs-derived HGF could regulate tumor metastasis by upregulating HK2, we first investigated whether a HGF neutralizing antibody could inhibit the upregulation of HK2 expression by GCMSCs-derived HGF in HGC-27 cells in vitro." (PMID 33718248, 2021). "Furthermore, to explore the role of miR‐125b/HK2 axis in the anti‐tumour effect of hsa_circ_0001806 inhibition on HCC cells, miR‐125b inhibitor or HK2 overexpression vector was transfected into hsa_circ_0001806 silenced Hep3B cells." (PMID 34664737, 2021). "HK2 not only plays a role in physiological function of human normal tissues and organs, but also plays an important role in the glycolysis of tumor cells." (PMID 34708035, 2021). "Accordingly, in tumor cell antagomir treatment decreased miR-375 amounts in TAMs upon coculture and lowered LDHB expression, enhanced glycolytic activity as indicated by the enhanced mRNA expression of HK2 and MCT4, as well as enhanced lactate synthesis." (PMID 34158867, 2021). "It has been shown that HK2 inhibits OXPHOS and promotes tumor proliferation." (PMID 35004842, 2021). "Additionally, significant increase of expression in tumor tissues, high expression of GYS1, HK2 and SLC2A were significantly correlated with decreased survival of LIHC patients in the TCGA cohort." (PMID 34059694, 2021). "Tumor cells reduce STAT3 signaling, downregulate hexokinase 2, and reduce glycolysis." (PMID 34771503, 2021). "From the perspectives of tumor tissue and cell lines, we simultaneously found that BIRC5 and HK2 may increase tumor malignancy with MYCN amplification, whereas GRID2 and RNASEL were antagonistic to MYCN amplification." (PMID 34746127, 2021). "Furthermore, inhibiting the expression of HK2 in HGC-27 and MGC-803 cells decreased tumor migration induced by GCMSCs." (PMID 33718248, 2021). "Among glycolytic enzymes, HK2 prevailed in tumor cells rather than in stromal cells of primary and metastatic PDA." (PMID 33804240, 2021).
tumor (continued). "Tumor tissues with high c-Met expression level in TCGA have increased expression of H6PD, PDK2, PDK4, PDPR, PKLR, SLC2A2 genes whereas decreased expression of GYS1, HK1, HK2, SLC2A1, significantly." (PMID 34059694, 2021). "Indeed, alteration in the glycolytic pathway activation, such as hexokinase 2 (HK2), pyruvate kinase M2 (PKM2) and phosphofructokinase 1 (PFK1) induce glycolysis and provide pro-survival cues to tumor cells." (PMID 34650217, 2021). "Importantly, depletion of HK2/ROCK2 restored the blood vessel supporting function of TPC, while treatment of HK2 inhibitor induces MLC2-driven tumor vasculature remodeling to enhance chemotherapy delivery and efficacy against tumor growth." (PMID 34650057, 2021). "Glycolytic key enzymes such as hexokinase 2 (HK2), phosphofructosidase (PFK), and M2-type acetone kinase (PKM2) are tumor markers, and their expression and activity can affect tumor glycolysis, which in turn affects proliferation of tumor cells." (PMID 34556750, 2021). "A switch from GCK to HK2 isoenzymes is occurring during the transition from primary to tumor hepatocytes so that HCC cell lines express HK2 but no longer GCK." (PMID 33594203, 2021). "An alternative strategy for targeting HK2 in tumor cells is the use of specific peptides that displace HK2 from OMM without affecting the catalytic activity of any HK." (PMID 33946854, 2021). "However, a study showed that HK2 was upregulated but HK1 was downregulated to increase glycolysis and accelerate tumor growth and metastasis." (PMID 32802843, 2020). "RNA-seq data also showed that THZ1 could diminish transcripts of MYC-targeted genes, such as HK2, CDC25A, GLUT1 (SLC2A1), PD-L1 (CD274), BRCA1, and BRCA2, which are important mediators of MYC’s function in tumor metabolism, immune evasion, and DNA repair." (PMID 32690037, 2020). "Moreover, HK2 silencing can synergistically enhance the sensitivity of HCC to sorafenib, thereby inhibiting tumor growth in mice." (PMID 32631382, 2020). "Besides its role in hypoxia and angiogenesis, HIF1α is also a potent activator of key glycolytic genes, among which are hexokinase 2 (HK2) and pyruvate kinase M2 (PK-M2; a tumor-specific isoform of PK), as demonstrated in Hep3B cells." (PMID 32932781, 2020). "Collectively, our results established FOXE1 as a critical tumor suppressor, regulating CRC cell growth and aerobic glycolysis through FOXE1/HK2 axis, which therefore could be a promising therapeutic target for CRC." (PMID 31918722, 2020). "In the past decade, many enzymes involved in glucose and lipid metabolisms have become the focus of research, including pyruvate kinase M2 (PKM2), hexokinase-2 (HK-2), and isocitrate dehydrogenase (IDH1/2), and all of them have been reported as new targets of tumor-targeted therapy." (PMID 32238881, 2020). "In line with a recent study, we showed that THZ1 could suppress tumor glucose metabolism in NSCLC cells, which may depend on downregulating MYC-targeted genes including HK2, GLUT, and CDC25A." (PMID 32690037, 2020). "Consistently, many genes coding for key glycolytic enzymes such as GLUT1, HK2, PFKFB3, PFKP, and PKM2 were significantly upregulated in HCC192Low tumors compared to HCC192High tumors but showed negligible alteration in their non-tumor tissues." (PMID 33256802, 2020). "HIF1A and HK2 were important glycolysis regulated genes, VEGFA was tumor angiogenesis gene." (PMID 33197880, 2020). "More importantly, HK2 was also increased in tumour cells under LSS independent of ATOH8 overexpression." (PMID 32000836, 2020). "We then further compared the HK2 expression level in the tumour from these 38 patients with or without GBM recurrence." (PMID 32279420, 2020).
tumor (continued). "A series of elegant experiments has unequivocally shown that glycolytic metabolism activates the YAP/TAZ signal in cells of different neoplasms (e.g., breast and liver) and YAP activation upregulates the expression and transcriptional activity of HK2 and PFKFB3." (PMID 33008042, 2020). "In addition, the expression levels of miR-103a-3p and the key glycolytic molecules HK2, LDHA and PFK1 in tumour tissues from miR-103a-3p antagomir group were lower than control values." (PMID 33218358, 2020). "The results indicate that the expression of HK2 and/or HKDC1 may contribute to tumor growth in ENKTL cells." (PMID 32203147, 2020). "Finally, the anticancer potency of kaempferol was further confirmed in a mice xenograft model, revealing the ability to significantly prevent the growth of tumor size coupled with a marked decrease in hexokinase-2 expression and EGFR activity in tumor tissues." (PMID 31248102, 2019). "Thus, HectH9-mediated HK2 ubiquitination drives apoptosis resistance, promotes glycolysis and ROS-regulated CSC self-renewal, in turn leading to tumor progression." (PMID 31201299, 2019). "Systemic ablation of HK2 in genetic mouse models inhibits tumor development without adverse physiological outcomes." (PMID 31201299, 2019). "The systemic deletion of HK2 in adult mice does not elicit adverse physiological consequences but inhibits tumor development in mouse models of cancers, where HK2 is highly expressed compared to normal cells." (PMID 29352298, 2018). "Finally, we found that HK2 KD in combination with sorafenib, the only FDA-approved drug for HCC, markedly increased HCC cell death and tumor growth in vivo." (PMID 29386513, 2018). "In addition, we also determined that the expression of the enzymes GLUT1, HK2, PKM2, and LDHA decreased in tumor tissue sections from the xenografts formed by GPx1 silencing in SW1990 cells." (PMID 30538220, 2018). "Moreover, inhibition of hexokinase 2 (HK2), the first rate-limiting enzyme of glycolysis, contributed to suppressing HPV16 E7-induced glycolytic phenotype of tumor metabolism and inhibited tumor cell growth." (PMID 30356100, 2018). "The results presented here suggest that the systemic deletion of HK2 will not interfere with the immune response towards such tumor cells." (PMID 29352298, 2018). "In the current study we therefore hypothesized that in cancer cells the free βII-tubulin can compete with HK-1 or HK-2 for the binding sites on VDAC(s) consequently, in order to regulate the aerobic glycolytics in tumor cells." (PMID 29998379, 2018). "Our results that the combination of sorafenib and HK2 silencing markedly increased HCC cell death and synergistically inhibited tumor growth suggest that HK2 inhibition could significantly increase the efficacy of sorafenib." (PMID 29386513, 2018). "Therefore, to clarify the possible role of βII-tubulin and HK-2 in the regulation of VDAC permeability for ADP, tumor cells were titrated with ADP." (PMID 29998379, 2018). "Due to its lower Km for glucose, HK1 rather than HK2 is required for tumour cell survival when glucose is scarce." (PMID 28054552, 2017). "The presence or absence of HK2 and LC3B protein expressions was associated with tumor stage, T status and metastasis." (PMID 29285270, 2017). "GLUT1, HK2, and LDHA were previously found to be regulated in an oncogenic Kras dependent manner, suggesting that they may be important for KRAS-driven tumor growth." (PMID 28915575, 2017).